IL5 (interleukin 5)
Diseases named in the same sentence as IL5 in open-access papers (continued):
Sharing a sentence is not in itself a finding about the gene and the disease.
Allergy (continued). "It is well recognized that allergic diseases are closely associated with an enhanced Th2 immune response with high levels of IL-4, IL-5, and IL-13, but accumulating evidence also implicates down-regulated Th1 immune responses in the pathogenesis of allergy." (PMID 25090641, 2014). "The aggravation was concomitant with the enhanced expression of allergy-associated cytokines, interleukin-5 (IL-5) and eotaxin, in the lung." (PMID 24137251, 2013). "The aggravation was concomitant with the amplified expression of the allergy-associated cytokines interleukin-5 (IL-5) and eotaxin, in the lung." (PMID 24137251, 2013). "It is well known that Th2 cells orchestrate allergy-induced asthmatic inflammatory responses, and the main immune abnormalities are caused by Th2 cytokines, such as IL-4 and IL-5, which induce eosinophil infiltration and airway hyperresponsiveness." (PMID 22545078, 2012). "In addition, IL-5 participates in the maturation and infiltration of eosinophils associated with allergic reactions." (PMID 37371997, 2023). "By contrast, clinical allergy is caused by dysregulated type 2 immunity, which is characterized by expansion of T helper 2 (Th2) cells and eosinophils, as well as overproduction of the associated cytokines IL-4, IL-5, IL-9, and IL-13." (PMID 35281022, 2022). "AR with neuroinflammatory markers may trigger allergies caused by IL-4, IL-5 and IL-6 and, thus, affect psychopathology, such as depression, that may be associated with increased inflammatory markers." (PMID 34689833, 2021). "As increased Th2-type IL-5 production is a hallmark of allergy, the use of BCG or, better yet, rBCG-hIL-18 may be a potential therapeutic tool to redress the Th1/Th2 immune balance in allergic patients." (PMID 33803752, 2021). "Indeed, IL-5 has been proposed as an important drug target for allergy and associated disorders and at least two antibodies against the IL-5 cytokine and its receptor are in clinical testing." (PMID 22989709, 2012). "Allergy is a type I hypersensitivity reaction involving Th2 cells that produce Interleukin (IL)-4, IL-5, IL-9, and IL-13." (PMID 41596388, 2026). "IL-5 plays a pivotal role in eosinophil inflammation, as eosinophils are end-stage effector cells of allergy." (PMID 41596388, 2026). "In a type I hypersensitivity allergic reaction, there is a Th2 immune response characterized by Th2 cells, eosinophils, basophils, IgE, IL-4, IL-5, and IL-13 serum elevation." (PMID 41596388, 2026). "It is well documented that patients with eosinophilic gastroenteritis demonstrate a high prevalence of allergy-related medical conditions, and IL-5 plays a crucial role in the pathogenesis of EGE." (PMID 40514730, 2025). "Other studies suggest the possible involvement of the Th2 pathway in non-IgE-mediated allergies, with findings of elevated serum levels of cytokines such as IL-3, IL-5, and IL-13 in patients with this type of allergy." (PMID 41394805, 2025). "(d) Using a recently developed humanized CFTR mouse model, we demonstrated an in vivo ivacaftor-mediated decrease in allergy through reductions in type 2 cytokines (IL-5 and IL-13) and total serum IgE." (PMID 40131363, 2025). "PeTh2 cells, with their strong IL‐5 production, play a critical role in mediating eosinophilic responses and are prominent in Type IVb allergic reactions." (PMID 40838325, 2025). "Recent studies have shown that biologics targeting IL-5 or IL-5RA can be adapted to treat various allergic diseases, including eosinophilic esophagitis." (PMID 40475764, 2025). "ILC2s and Th2 cells secrete IL-4, IL-5, and IL-13, which induce an inflammatory immune response that plays a key role in allergic reactions." (PMID 40290033, 2025). "IL-5 is essential to the pathogenesis of allergic disease, especially acting on the differentiation, recruitment, survival, and degranulation of eosinophils." (PMID 41301750, 2025).
Allergy (continued). "Emerging therapies include recombinant cytokines, exosomes, and monoclonal antibodies targeting IL-4/IL-13 or IL-5, which are mostly approved for the treatment of allergic diseases." (PMID 41007770, 2025). "Cytokine IL-5 is an important player in the pathogenesis of allergic diseases since this cytokine promotes eosinophilic maturation, survival and eosinophilic inflammation." (PMID 40718495, 2025). "NK cells proliferate in the presence of IL-4 and can contribute to the production of IL-4, IL-5, and IL-13 cytokines in an allergic reaction." (PMID 40718495, 2025). "Patients with EoG who have allergies possess a group of IL-5+ Th2 cells that are specifically targeted towards food allergens." (PMID 39136025, 2024). "The IL-4, IL-5, and IL-13 secreted by Th2 inhibit the activity of Th1 and stimulate B cells to produce IgG1 and IgE, and their secretion regulates the allergy-mediated Th1–Th2 balance, lymphocyte infiltration, and cytokine secretion." (PMID 38674852, 2024). "The AR response include high amounts of specific IgE in the serum, high amounts of allergy relative mediators (eosinophil peroxidase and tryptase), and Th2 cytokines (IL-4, IL-5, IL-13) in nasal secretions, and high total nasal symptom scores (TNSS)." (PMID 38783329, 2024). "IL-5 can influence the differentiation and activation of T-helper type 2 (Th2) cells, which play a role in the immune response to allergies and parasitic infections." (PMID 38393122, 2024). "IL-5 is responsible for the maturation, growth, activation, and survival of eosinophils, the effector cell during allergy." (PMID 39507249, 2024). "Investigation of IL-5 and the conduct of research on immunological pathways in allergic diseases can lead to the assumption that IL-5 is one of the main or initial points in the pathogenesis." (PMID 39062104, 2024). "Th2 cells induce the secretion of cytokines such as IL-4, IL-5, and IL-13, promoting the production of immunoglobulin (Ig) A and Ig E, thereby regulating humoral immune responses and allergic diseases." (PMID 39664894, 2024). "The occurrence of an allergic response can stimulate the release of type 2 inflammatory mediators, including IL-4, IL-5, and IL-13, which promote the recruitment and activation of eosinophils, mast cells, and basophils, thereby inducing nasal eosinophilia." (PMID 38070374, 2024). "In this review, we described in detail the structure, function, and subsequent role of IL-5 in the pathogenesis of various allergic diseases." (PMID 39062104, 2024). "The idea for this new application for anti-IL-5 was based on the significant role that eosinophils play in allergic diseases." (PMID 39062104, 2024). "TMPRSS2 reduces the recognition of viruses through human defense mechanisms; however, type 2 inflammation, in which interleukin (IL)-4, IL-5, and IL-3 are important inflammatory factors, acts as the inflammatory basis of allergic diseases in children." (PMID 38646512, 2024). "Th2 cells directly trigger the aggregation and activation of inflammatory cells by releasing IL-4, IL-5, IL-13, and other cytokines, and promote the occurrence of delayed airway allergic reactions." (PMID 38546350, 2024). "IL-5 has been considered a therapeutic target for allergic diseases because of the exclusive IL-5R expression in eosinophils and human basophils and its critical role in eosinophilopoiesis." (PMID 39840047, 2024). "The type‐2 response entails the generation of Th2 cytokines, like IL‐4, IL‐5, and IL‐13, which trigger the production of non‐opsonizing antibodies and allergic reactions, while also suppressing the pronounced inflammatory response induced by Th1 cytokines." (PMID 38774871, 2024). "Some biological agents that block Th2 response, such as anti-IL-4Rα mAb, anti-IL-5/IL-5R mAb, anti-IgE mAb, are used for patients with allergic diseases." (PMID 39483683, 2024).
Allergy (continued). "Similar to human allergic disease, canine allergy is characterized by increased expression of the type 2 cytokines IL-4, IL-5 and IL-13, e.g. in dogs with atopic dermatitis." (PMID 38835756, 2024). "IL-5 primarily promotes activation, survival and adhesion of eosinophils, and is therefore elevated in allergy and parasitosis." (PMID 37469521, 2023). "Here, we show that GJExCR treatment reduced the Th2-mediated immune response in OVA-induced allergy, including dampening of IL-4, IL-5, IL-10, IL-13, TNF-α, INF-γ, chemokine, and IgE expression, in both serum and spleens." (PMID 36980282, 2023). "In contrast, comorbid allergy, elevated tissue IL-5, or IgE levels (including specific IgE against S. aureus enterotoxins) were significant predictors of the need for revision surgery." (PMID 37569753, 2023). "Complications during pregnancy were linked to different pattern of the IFNG, IL5, IL4 and IL10 methylation depending on allergy status." (PMID 37520545, 2023). "This Th2 subset is responsible for the secretion of interleukin-4 (IL-4) and interleukin-5 (IL-5) cytokines, which play major roles in the regulation of lymphocyte proliferation, and atopic and allergic disease." (PMID 37701007, 2023). "In allergic reactions, allergens activate T cells to differentiate into Th2 cells and secrete IL-4, IL-5, and IL-13, leading to allergen-specific IgE production." (PMID 37101296, 2023). "The IL5 contributes to the development of allergic diseases via a very complicated process of inflammation engaging the T cells and granulocytes." (PMID 37520545, 2023). "IL-5, which plays an important role in several allergic diseases, has been shown to exert its protective effect in cancer through the involvement of eosinophils, which act in concert with other immune cells in regulating the antineoplastic immunity." (PMID 37686245, 2023). "Several studies have confirmed that higher expression levels of IL-4 and IL-5 will induce allergic diseases in infants." (PMID 36673400, 2023). "Type 2 immunity consists of GATA3+ Th2 cells and mediates allergy by producing IgE antibody as well as IL-4, IL-5, and IL-13." (PMID 35484967, 2022). "Tregs secrete regulatory cytokines such as and IL-10 and TGF-β, which reduce pulmonary eosinophil infiltration, allergy-specific Th2 cytokines (IL-4, IL-5, and IL-13), allergy specific IgG1 and IgE production, allergic rhinitis symptoms, and AHR." (PMID 36556359, 2022). "The results of a study show that intranasal use of SP-D reduced inflammatory symptoms and allergies in mice and also reduced IL-2, IL-4, IL-5, and eosinophil levels." (PMID 35419072, 2022). "Increases in eosinophil cationic protein (ECP), interleukin (IL)-5, eosinophils, and total IgE in children with KD were considered markers of allergy." (PMID 36077487, 2022). "TH2-type CD4+ T cells and the cytokines that produce IL-4, IL-5, and IL-13 are considered major players in the pathophysiology of allergic diseases." (PMID 36364962, 2022). "In contrast, Th2 cells, which produce IL-4, IL-5, IL-6, IL-9, IL-10, and IL-13, induce strong antibody responses by B cells, induce eosinophil activation, and are responsible for allergic reactions." (PMID 35646978, 2022). "The aim of this study was to evaluate organ manifestation of an allergic reaction in the wall of the appendix (eosinophil infiltration) through sequential phases of AA and search for a possible correlation with IL-5 present in ALF and in the blood." (PMID 36499410, 2022). "Anti-IL5 for KD patients with an iEOS phenotype or in KD patients with prognostic biomarkers of future allergic diseases would be considered." (PMID 36077487, 2022). "In response to various cytokines released by Th2 cells, such as IL-4, IL-5, IL-5 and IL-13, many inflammatory cells are activated, which in turn elicit an inflammatory response that leads to the clinical symptoms of allergic disease." (PMID 35572600, 2022).
Allergy (continued). "In a prior study, CD34+ stem cells from blood donors express ST2L and produce IL-5 and IL-13 in response to IL-33 supporting these stem cells as potential effector cells in allergic diseases." (PMID 36177009, 2022). "The type 2 Th (Th2) dominance is a key feature of atopy or allergy as these cells predominantly produce interleukin 4 (IL-4), IL-5, and IL-13, which are involved in the initiation and perpetuation of the allergic phenotype." (PMID 33668787, 2021). "IFN‐γ inhibits the collection of eosinophils by inhibiting CD4+ T cell infiltration, reducing IL‐4 and IL‐5 production, inhibiting the synthesis of IgE, and attenuating allergy‐induced airway inflammation." (PMID 33421348, 2021). "On the other hand, Type 2 T-helper (Th2) cells mainly secrete interleukins (ILs) including IL-4, IL-5, and promote B cells to secrete immunoglobulin E (IgE) antibodies to promote humoral immunity and induce allergy response." (PMID 33535602, 2021). "In this study, we demonstrate in a model of HDM allergy that in the presence of Der p 1, the IL-5 production by naïve T cells from allergic patients was significantly decreased by BCG and even more by rBCG-hIL-18." (PMID 33803752, 2021). "Pro-inflammatory cytokines (e.g., IL-12, IL-25 and IL-13) play an important role in driving allergic conditions including allergic asthma; IL-33, IL-4 and IL-5 are key factors that drive allergy." (PMID 34638811, 2021). "Fish oil supplementation in infants at high risk of atopy increased ω-3 PUFA levels and decreased allergen-specific Th2 responses, including IL-13 and IL-5 production, thus suggesting a potential protection against allergy." (PMID 33668787, 2021). "Mediators of allergic disease include allergen-specific IgE, chemokines that recruit eosinophils and IL-5 that induces eosinopoiesis." (PMID 34368802, 2021). "ILC2s respond quickly to allergic reactions mainly by secreting type 2 cytokines and other peptides, such as IL-4, IL-5, IL-13, IL-9, and amphiregulin (Areg), and by intercellular regulation of the cell-to-cell pathway." (PMID 34177881, 2021). "Anti-IL-5 antibodies block IL-5 and reduce eosinophil levels of blood, bone marrow and tissue, and some studies have shown the efficacy and safety of these agents in patients with allergic diseases and hypereosinophilic syndrome." (PMID 34784964, 2021). "The potential links between these allergic diseases point to a number of attractive therapeutic targets, including IgE antibodies, IL-5, and eosinophils, which are stimulated through the cell surface receptor, IL-5R." (PMID 33673870, 2021). "Cytokines and chemokines involved in tissue injury, infection, and allergic disease, such as IL-5, LIF, LIX, MCP-1, MIP-1a, and MIP-1b, were increased in the USA300-C2406-infected mice." (PMID 33573328, 2021). "Several pharmaceutical agents have been approved or are currently in development that are designed to disrupt the IL-5/IL-5R interaction in eosinophilic asthma, AD, or other allergic diseases." (PMID 33673870, 2021). "ILC2s synthesize and secrete Th2 cytokines (IL-4, IL-5, IL-9, and IL-13), which promote eosinophils and mast cells to participate in allergic reactions." (PMID 34659628, 2021). "These cells produce cytokines characteristic of the Th1-dependent response (IL-2, IFN-γ) and Th2 cells (IL-4, IL-5, IL-10) so they can play both protective and pathogenetic roles in allergic diseases, depending on the disease phase." (PMID 33435598, 2021). "Allergy is characterized by the activation of CD4+ Th2 cells and the production of Th2 associated cytokines, such as IL4, IL5, and IL13, as well as levels of IgE, which activates mast cells." (PMID 33255731, 2020). "Th2-related cytokine (IL-4/IL-5) was increased by the allergy induction and aggravated by E2 treatment, while administration of API inhibited its level." (PMID 32765268, 2020).
Allergy (continued). "Eosinophils are also present in healthy individuals, but in allergic diseases the release of various mediators such as IL-5, IL-3, and GM-CSF promotes the production and activation of the cells." (PMID 32280308, 2020). "Th2 cells can also be regulated by the transcription factor GATA-3 and secrete IL-4, IL-5, IL-13 and other effector cytokines to regulate allergic reaction." (PMID 33194780, 2020). "IL-5 plays a critical role in adaptive immune responses since it regulates eosinophils, cells that play a central role in the pathogenesis of allergic diseases, and induces cell maturation, survival, and activation." (PMID 31973090, 2020). "It is established knowledge in the allergy field that Th2-derived IL-9 and IL-4/IL-5 induce goblet cell hyperplasia either directly or indirectly via neutrophilic granulocytes, respectively." (PMID 30845208, 2019). "Th2 are closely involved in allergy; their immune response involves the production of IL-4, IL-5, and IL-13, which lead to the recruitment and activation of mast cells, basophils and eosinophils, and goblet cell hyperplasia in airway mucosa." (PMID 31683763, 2019). "IL-5 is the major eosinophil and mast cell chemotactic cytokine and plays a critical role in allergy and OM (28, –, 30)." (PMID 31548315, 2019). "ILC2s are key drivers of allergic disease and upon activation express very high levels of IL-5, IL-6, and IL-13, but also secrete many other cytokines, including IL-4, GM-CSF, IL-9, and IL-10." (PMID 31024538, 2019). "The roles for IL-4, IL-5, IL-13, and GM-CSF in allergic diseases are well established, and it is clear that iBET151 has the potential to suppress these responses in ILC2." (PMID 31024538, 2019). "TSLP is widely known to induce Th2 responses by elevating Th2 cytokines such as IL-4, IL-5, and IL-13 in allergic diseases, including AD." (PMID 31817146, 2019). "Th2 interleukins such as IL-4 and interleukin 5 (IL-5), leads to immunoglobulin E (IgE) production and inducing of the growth of mucosal-type mast cells which can resulted in allergic response." (PMID 31156785, 2019). "In the late phase allergic reaction, Th2 cells and mast cell-derived cytokines namely IL-3, IL-5 and GM-CSF are involved in the eosinophil activation and recruitment of leukocytes to the region of allergen exposure." (PMID 31694050, 2019). "Whereas, late phase of the allergic reaction is recognized by the release of cytokines such as IL-13, IL-4, IL-9, IL-5, IFN-γ and TNF-α after 2 to 6 h of sensitisation." (PMID 31829185, 2019). "Meanwhile, the late phase of an allergic reaction occurring hours after sensitisation will trigger the release of cytokines such as IL-4, IL-5, IL-9, IL-13, TNF-α and IFN-γ that will recruit inflammatory cells and further bring about mast cell degranulation." (PMID 31829185, 2019). "Similar results have been reported by our group in a BLG-sensitized mice model, in which we found that the administration of LGG added to EHCF elicited a significant reduction of allergic reaction, and of IL-4, IL-5, IL-13 and specific IgE production." (PMID 30828329, 2019). "More recently, mitochondrial Ca2+/calmodulin-dependent protein kinase II has emerged as key mediator of the molecular response in allergy, regulating eotaxin, IL-4, IL-5, IL-13, and eosinophilic inflammation." (PMID 29890625, 2018). "Tregs36 and Bregs37 as sources of immunomodulatory cytokines IL-10 and TGFb counterregulate the Th2 cytokine dominance in allergy, including the Th2 cytokine IL-5." (PMID 28566688, 2017). "Among children over 36 months, those in the recurrence group had more allergic disease and higher IgE, IL-4, and IL-5 levels than the same-aged children in control group." (PMID 28418014, 2017). "IL-5 is essential for eosinophil survival in humans and B cell development in mice, and it plays a detrimental role in allergic diseases and parasite infection." (PMID 29156632, 2017).